HIF1A (hypoxia inducible factor 1 subunit alpha)
Diseases named in the same sentence as HIF1A in open-access papers (continued):
Sharing a sentence is not in itself a finding about the gene and the disease.
tumor (continued). "HIF-1α deficiency in ECs hampers tumor cell migration through endothelial layers, while loss of HIF-2α enhances tumor cell migration and metastasis." (PMID 29434587, 2018). "The reduced AQP1‐dependent tumour angiogenesis caused a hypoxic condition, evaluated by HIF‐1α significant increase, in turn causing an increased level of apoptosis in AQP1 KD tumours, assessed by CASP3 quantification and DNA fragmentation." (PMID 29044946, 2018). "We found that a high staining with anti-HIF-1α in tumor hypoxic zone associated with a high expression of genes belonging to the hypomel signature." (PMID 29312568, 2017). "Our results confirmed that increased tumor hypoxia and the resulting elevation of HIF-1α expression in our experimental mice were associated with increased VEGF-A expression, an outcome consistent with the extensive literature on this topic." (PMID 28788063, 2017). "Consistent with our results, loss of HIF-1α in NK cells resulted in a decrease of pericyte coverage, along with increased hypoxia and tumour cell death." (PMID 29150606, 2017). "As one of the hallmark of tumor, neovascularization is a well-known downstream event of activated HIF-1a through up-regulation of erythropoietin, vascular endothelial growth factor and its receptor." (PMID 28099905, 2017). "Hypoxia is a hallmark for cancer cells, and HIF1α is largely responsible for alterations in metabolism that support the survival of hypoxic tumor cells." (PMID 28594405, 2017). "HIF1α-mediated high expression of MCT4 has been reported in pancreatic ductal carcinoma-associated CAFs indicating an active lactate transport within tumor stroma." (PMID 28447025, 2017). "In tumor grafts, however, the emodin- and rhein-induced decrease in HIF-1α expression was associated with a decrease in total Akt but not p-Akt." (PMID 29152137, 2017). "Loss of KDM4A in hypoxic conditions leads to a decreased HIF-1α mediated transcriptional response and correlates with a reduction in the characteristics associated with tumour aggressiveness, including invasion, migration, and oxygen consumption." (PMID 28894274, 2017). "It has been reported that loss or mutation of pVHL remarkably enhances HIF-1α protein accumulation, and tumor angiogenesis, proliferation and metastasis, supportting that preventing pVHL protein loss is capable of attenuating tumorigenesis." (PMID 28710377, 2017). "The expression of TWIST1 is also regulated by Hypoxia-inducible factor (HIF)-1α, a protein associated to hypoxic tissue areas and related to proliferation, differentiation, and development of an aggressive tumor phenotype." (PMID 29152120, 2017). "Pooled OR was 2.28 (95% CI = 1.49–3.50, I2 = 55.2%, P = 0.017; random-effects model), which suggested an association between HIF-1α expression and tumor size." (PMID 28521842, 2017). "Consistent with TCGA analysis, SqCC tumours exhibit increased AKT signalling activities compared to ADC tumours, which is strongly associated with HIF-1α expression." (PMID 28548087, 2017). "BAF180 KO/HIF1A cDNA 786-O cells exhibited increased cell survival/proliferation, compared with BAF180 WT/HIF1A cDNA 786-O cells, demonstrating that loss of the tumor-suppressive activity of BAF180 in H2 ccRCC cells is due to the loss of HIF1A gene expression." (PMID 28092369, 2017). "HIF-1α-deficient tumor-infiltrating CD8+ lymphocytes were characterized by a drop in expression of the costimulatory molecules CD137 and GITR, and in the checkpoint receptors PD-1, LAG3, and TIM3." (PMID 29136509, 2017). "The composition of tumor-infiltrating lymphocytes in these experimental tumors was lower in CD8+ T cells in mice deficient in HIF-1α in T cells, and there was a diminished CD8+-to-CD4+ T cell ratio." (PMID 29136509, 2017). "HIF1α has a well-described role in supporting cellular survival in the hypoxic tumor micro-environment, a mechanism well-linked to radio-resistance and tumor metastatic potential." (PMID 28915708, 2017).
tumor (continued). "Studies have investigated that tumor-associated hypoxia results in upregulation of hypoxia-inducible factor-1α (HIF-1α), which subsequently leads to upregulation of several molecular mediators, e.g., vascular endothelial growth factor (VEGF)." (PMID 29258180, 2017). "This indicates that loss of HIF1α in NK cells increases the metastatic index, which defines the relation between metastatic burden relative to tumour volume." (PMID 29150606, 2017). "In contrast to HIF-1α-deficient tumor-infiltrating CD8+ T cells, however, PD-1 expression in VEGF-deficient tumor-infiltrating lymphocytes (TILs) is unaffected and there are no changes in FOXP3 expression levels in infiltrating CD4+ T cells." (PMID 29136509, 2017). "HIF-1α has been reported to play a key role in the regulation of genes associated with angiogenesis, tumor resistance, invasion and metastasis under hypoxia conditions." (PMID 28069592, 2017). "HIF-1α plays a central role in tumor progression by activating target genes that are associated with oxygen homeostasis and angiogenesis." (PMID 29333211, 2017). "HIF‐1α is a key cellular survival protein under hypoxia and is associated with tumor progression and metastasis in various solid tumors." (PMID 28401704, 2017). "Ten studies had assessed the association between HIF-1α expression and tumor size (T3/T4 vs. T1/T2)." (PMID 28521842, 2017). "Knockdown of CHCHD4 correlated with reduced tumor progression and was linked to the stability of HIF1A (hypoxia-inducible factor 1 alpha subunit), one of the central players of the HIF pathway response to hypoxia." (PMID 28701417, 2017). "It has been reported that tumor-specific accumulation of heptamethine cyanine dye is closely associated with the activation of HIF1α and organic anion-transporting polypeptide (OATPs)." (PMID 28635650, 2017). "Deletion of the JunD gene in the stroma promoted tumor growth and metastasis, associated with increased ROS production, with consequent accumulation of HIF1α and HIF1α-dependent induction of CXCL12, activating CXCR4, promoting CAF differentiation." (PMID 29137220, 2017). "It has been suggested that HIF-1α is overexpressed in different tumor types and is implicated in excessive vascularization and tumor invasiveness." (PMID 28881698, 2017). "HIF-1α is a crucial transcription factor that contributes to the tumor EMT, which is characterized by the loss of cell adhesion, repression of E-cadherin expression, acquisition of the mesenchymal marker vimentin, and increased cell motility and invasiveness." (PMID 28449718, 2017). "Although elevated levels of tumor HIF-1α and HIF-2α have been associated with poor patient survival in multiple tumor types, HIF-1α and HIF-2α have distinct functions regarding inhibition or promotion of cancer growth." (PMID 28572533, 2017). "Large tumors are usually accompanied by a hypoxic condition, which is known to induce the expression of hypoxia-induced factor 1α (HIF1α) that is associated with tumor size and promotes the expression of GLUT1 in HCC." (PMID 28036362, 2016). "Knock-in mice bearing a methylation-defective Hif1aKA/KA allele exhibit enhanced retinal angiogenesis and tumour vascularization via HIF-1α stabilization." (PMID 26757928, 2016). "Mechanistically, a loss of Hif-1α in macrophages attenuated their ability to suppress T-cell proliferation and activation in vitro thus, favoring cell death at early stages of PyMT tumor progression, assumingly lowering tumor mass in vivo." (PMID 27015123, 2016). "A significant decrease was observed in cells silenced for β-arr1 or HIF-1α, or treated with macitentan, indicating that tumor cells require the association of HIF-1α with β-arr1 for a full transcriptional response to ET-1/ETAR axis." (PMID 26909598, 2016). "HIF-1α has been implicated as a tumor promoter, while it has been suggested that HIF-2α act as a tumor suppressor gene." (PMID 26846782, 2016).
tumor (continued). "Increasedlevels of HIF-1α are associated with increased proliferation and more aggressive breast tumordevelopment." (PMID 27540529, 2016). "Hypoxia inducible factor-1α (HIF-1α) increases tumor angiogenesis and tumor tissue expression is associated with reduced survival." (PMID 26937938, 2016). "Cells were transplanted into wild-type mice through orthotopic or portal vein injection in order to test the in vivo function of Hif1α in two major tumour-associated biological scenarios: primary tumour growth and remote colonization/metastasis." (PMID 27941931, 2016). "Both HIF-1α and Axl influence tumor growth and metastatic potential, and they have been linked to treatment failure in many cancers." (PMID 26760782, 2016). "It was also established by another study that functional polarization of tumor-associated macrophages is mediated by tumor-derived lactic acid that is regulated by HIF1α." (PMID 27774525, 2016). "The increased proliferation of tumor cells, in which HIF1α is active, is also linked to the metabolic reprogramming of these cells." (PMID 26798421, 2016). "In conclusion, we show that high stromal HIF-1α expression predicts reduced survival in EC and is associated with increased tumor metabolism at FDG-PET/CT." (PMID 27634881, 2016). "Combined with our findings, this suggests that VHL loss creates an environment where HIF-1α expression drives tumour metastasis and HIF-2α promotes tumour growth." (PMID 27358011, 2016). "MTA1 increases the expression of histone deacetylase-1 and causes deacetylation of HIF-1α, which is involved in tumor angiogenesis." (PMID 26878004, 2016). "They identified CUL2 frameshift mutations in colon cancers and suggested that mutations inactivate the tumor suppressor function of CUL2 through HIF-1α proteolysis." (PMID 26983985, 2016). "Taken together, these findings indicate that HIF-1α methylation deficiency promotes tumour angiogenesis, thereby accelerating tumour growth." (PMID 26757928, 2016). "A number of single nucleotide polymorphisms (SNPs) associated with tumor progression have been identified in the HIF-1α gene." (PMID 26872370, 2016). "The oncometabolites succinate and fumarate, which both accumulate due to mutations inactivating SDH or FH, inhibit HIF1α degradation, so causing pseudo-hypoxia and favouring tumour progression." (PMID 27083002, 2016). "Since HIF-1α and tumor hypoxia are considered to be associated with tumor progression, it would be beneficial to downregulate HIF-1α under hypoxic conditions as seen in the current study." (PMID 27286880, 2016). "We further validated these results by quantifying Ki67 and CC3 expression and found that in accordance with our previous results, decreased HIF-1α expression in RKO tumours was associated with decreased proliferation (Ki67) and elevated apoptosis (CC3)." (PMID 27966538, 2016). "Immunoblot analysis confirmed that the IDH1-mutant GBMs had significantly reduced total tissue HIF1α protein suggesting a profound dysregulation of the hypoxic response in xenograft tumours expressing the R132H IDH1 mutation." (PMID 27820599, 2016). "It has been demonstrated to be regulated by the Hypoxia-inducible factor 1-α (HIF-1α), a crucial transcriptional factor implicated in tumor progression and cancer angiogenesis." (PMID 26882120, 2016). "In this study we sought to explore the underlying mechanisms through which TM inhibits tumor angiogenesis, with special attention to its ability to suppress HIF-1α protein expression." (PMID 26469226, 2015). "Adding to this complexity is that HIF-1α apparently possesses tumor-suppressing activities, as indicated by the loss-of-function mutations or even homozygous deletion of HIF1A in certain human cancers." (PMID 25893706, 2015).
tumor (continued). "We next performed metabolomic analyses on TRACK kidney samples to determine if the increases in mRNA levels observed for HIF1α target genes implicated in altered tumor metabolism are, in fact, associated with changes in metabolite levels in the TRACK kidneys." (PMID 25830305, 2015). "Several studies have indicated that HIF-1α expression is strongly associated with tumor initiation, malignant progression, and resistance to radiotherapy and chemotherapy." (PMID 25929338, 2015). "HIF-1α regulates the epithelial-mesenchymal transition (EMT) that is one of the crucial mechanisms to cause early stage of tumor metastasis." (PMID 26115041, 2015). "Loss or mutation of the remaining wild-type allele results in constitutive expression of HIF-1α, which is a key modulator of tumor metabolism." (PMID 26474388, 2015). "Bevacizumab-induced reductions in tumour perfusion were significantly associated with increased HIF1α or CA9 expression in primary liver cancer." (PMID 25700172, 2015). "Our data thus provides novel insight into the mechanism underlying the metformin-induced inhibition of tumor angiogenesis and indicates possibilities of HIF-1α-VEGF signaling axis in mediating HER2-induced tumor angiogenesis." (PMID 26625311, 2015). "Elevated HIF-1α expression is associated with tumor metastasis, resistance to therapy and poor survival." (PMID 25843954, 2015). "An example of this effect is highlighted when a mutation in the von-Hippel Lindau (VHL) tumor suppressor leads to elevated levels of HIF-1α." (PMID 25809609, 2015). "Various genes specifically expressed in BMDCs have been associated with tumor aggressiveness such as Ets2, Vegf, Hif1α, and Atf-3." (PMID 26497998, 2015). "A number of SNPs associated with tumor development and progression have been identified in the HIF1A gene." (PMID 26115041, 2015). "In different types of tumours, even in conditions of normoxia, the HIF-1α protein levels are elevated, resulting from loss-of-function mutations targeting its negative regulator VHL tumour suppressor." (PMID 26339588, 2015). "STAT3/HIF-1α axis has been implicated in a number of cellular functions including tumor growth and metastasis." (PMID 26370982, 2015). "The hypoxic environment in tumors is an important factor that causes tumor metastasis by activating HIF-1α." (PMID 26047481, 2015). "Vhl mutant zebrafish has been previously shown to exhibit a systemic hypoxic response with increased levels of Hif-1α seen in vhl deficient tumours." (PMID 26559940, 2015). "Once again, our results are in agreement with previous reports pointing out the relevance of NFκB in tumor progression in HIF-1α-deficient tumors." (PMID 26696754, 2015). "Previous studies have demonstrated that LW6 exerts marked anti-tumor efficacy in vivo and causes reductions in HIF-1α expression levels in mice carrying xeno-grafts of HCT116 cells." (PMID 26017562, 2015). "HIF-1α is a key cellular survival protein during hypoxia, and is associated with tumor progression and metastasis in various solid tumors." (PMID 25993275, 2015). "Increased expression of the cancer stem cell-associated membrane protein CD24 correlates with tumor aggressiveness; it is also a direct target of HIF-1α and participates in tumor growth and metastasis." (PMID 26056085, 2015). "Both hypoxia (and HIF-1α pathway) and CA IX protein have been associated with chemoresistance in various tumor types." (PMID 25955133, 2015). "In the tumor microenvironment, HIF-1α expression in tumor-associated macrophages suppresses T cell responses and induces expression of arginase 1; HIF-1α also enhances the inhibitory effect of MDSC." (PMID 26046638, 2015). "HIF1α accumulation in tumors can be induced by various stress signals, including hypoxia in tumor microenvironment, loss of a tumor suppressor, or oncogene activation." (PMID 25622105, 2015).
tumor (continued). "Previous studies have shown that HIF-1α is strongly associated with tumor propagation, malignant progression, and resistance to radiotherapy and chemotherapy." (PMID 25929338, 2015). "HIF-1α is frequently upregulated at protein level in response to the hypoxic tumor environment and this overexpression has been associated with an aggressive phenotype, namely resistance to chemotherapy and poor outcome in a wide range of tumors." (PMID 24629239, 2014). "It was reported that HIF-1α null mutations severely retard tumour growth by reducing the expression of VEGF and that overexpression of HIF-1α is associated with resistance to cancer chemotherapy and increased patient mortality." (PMID 24895555, 2014). "Whereas NTC cells formed tumors in the all of the injected mice by 71 d after injection, HIF-1α knockdown cells showed a complete loss of tumor-initiating ability and knockdown of TAZ or HIF-2α impaired, but did not eliminate, tumor formation." (PMID 25587023, 2014). "HIF-1α induced proangiogenic factors such as VEGFR1, PDGF-B, and angiopoietins, and HIF-1α expression in MDSCs, was associated with immunosuppressive function and tumor progression." (PMID 25514597, 2014). "The HIF-1α subunit is over-expressed in many human cancers, due in large part to extensive areas of tumor hypoxia and loss-of-function and gain-of-function mutations in genes regulating HIF-1α." (PMID 25350400, 2014). "Recent studies that focused on the relationship of HIF-1α tumor expression to the response to chemotherapy or hormone therapy found that increased levels of HIF-1α were associated with resistance." (PMID 25112709, 2014). "In an environment of local oxygen deficiency or tumor growth, HIF-1α, as an important transcription factor for the regulation of oxygen homeostasis, is upregulated." (PMID 25371752, 2014). "HIF-1α promotes tumor angiogenesis and growth by promoting tumor angiogenesis and metabolism-associated gene transcription." (PMID 24669250, 2014). "In this study, the underexpression of BECN1 was correlated with poor prognosis, whereas the extensive overexpression of BECN1 was associated with the tumor HIF-1α level and aggressive clinical behavior." (PMID 24723943, 2014). "Mounting evidence suggests that hypoxic tumor microenvironments, especially the overexpression of HIF-1a, are strongly implicated as the hallmark of a wide variety of human malignancies." (PMID 24647137, 2014). "Hypoxia and oxygen radicals co-operatively promote tumor angiogenesis and cause the activation of HIF-1α, which in turn stimulates VEGF expression." (PMID 24614305, 2014). "A recent research in cancer has indicated that tumor necrosis factor receptor-associated factor-6 (TRAF6) will promote tumor angiogenesis as it will upregulate the expression of hypoxia-inducible factor-1α (HIF-1α)." (PMID 25089269, 2014). "Hypoxia-inducible factor-1α (HIF-1α) is overexpressed in many human tumors and their metastases, and is closely associated with a more aggressive tumor phenotype." (PMID 25295523, 2014). "We first compute the effects of this therapy on nuclear HiF-1α normoxic level for a tumor cell presenting a deregulation of HiF-1α expression (-mutated cells)." (PMID 25338163, 2014). "Studies have been shown that hypoxia-inducible factor-1α (HIF-1α) can induce tumor cells to form vessel-like tubes and express genes associated with VM." (PMID 25984487, 2014). "The hypoxic microenvironment plays a major role in controlling the tumor stem cell phenotype and is associated with patients' prognosis through hypoxia-inducible factor-1α (HIF-1α), a key transcriptional factor that responds to hypoxic stimuli." (PMID 25142304, 2014). "The data supports the notion that a substantial proportion of HIF-1α in the majority of tumours is proline-hydroxylated and that hypoxia can cause the degradation of proline-hydroxylated HIF-1α to be rate limiting." (PMID 24563687, 2014).